FGF12 (fibroblast growth factor 12)
Diseases named in the same sentence as FGF12 in open-access papers (continued):
Sharing a sentence is not in itself a finding about the gene and the disease.
psoriasis (1 paper, 2024). An autoimmune condition characterized by red, well-delineated plaques with silvery scales that are usually on the extensor surfaces and scalp. "To investigate the association between psoriasis and FGF12, we initially analyzed the expression pattern of FGF12 in skin biopsies." (PMID 39234815, 2024). "Further investigations are needed to fully understand the specific functions of FGF12 in the skin and the underlying mechanisms, particularly in the context of psoriasis." (PMID 39234815, 2024). "To understand the influence of FGF12 on the inflammatory response associated with psoriasis development, we examined the gene expression levels of various inflammatory markers by qRT‐PCR." (PMID 39234815, 2024). "Fibroblast growth factor 12 (FGF12) is implicated in the regulation of diverse cellular signals; however, its precise mechanism in psoriasis requires further investigation." (PMID 39234815, 2024). "Moreover, specific loss of FGF12 in keratinocytes in IMQ‐induced psoriasis model alleviates psoriasis‐like symptoms and reduces proliferation." (PMID 39234815, 2024). "In this study, we aimed to investigate the abnormal expression of FGF12 in psoriatic keratinocytes and its potential role in the treatment of psoriasis." (PMID 39234815, 2024). "Further investigations are needed to explore the potential involvement of FGF12 in psoriasis and its clinical significance." (PMID 39234815, 2024). "FGF12 is abundantly expressed in psoriasis and is found in close proximity to epidermal keratinocytes." (PMID 39234815, 2024). "This positive regulatory loop highlights the potential of FGF12 as a therapeutic target to manage psoriasis." (PMID 39234815, 2024). "Consistently, western blot analysis revealed that FGF12 expression was significantly higher in IMQ‐induced psoriasis mice than in normal control mice." (PMID 39234815, 2024). "Analysis of the Gene Expression Omnibus dataset GSE14905 revealed that Fgf12 mRNA expression was significantly higher in lesional skin than in non‐lesion skin from psoriasis individuals." (PMID 39234815, 2024). "Immunofluorescence staining showed that the FGF12 positive signal (red) predominantly co‐localized with the Krt14 positive signal (green) in the epidermis of both human psoriasis skin and the IMQ‐induced mouse model." (PMID 39234815, 2024).
psoriasis (continued). "Taken together, these data demonstrate that expression of FGF12 is upregulated in lesions and correlates with the exacerbation of psoriasis." (PMID 39234815, 2024). "FGF12 is upregulated in the epidermis of patients with psoriasis and the imiquimod‐induced mouse model." (PMID 39234815, 2024). "In conclusion, these findings collectively indicate that FGF12 plays a crucial role in the pathogenesis of psoriasis by influencing the cell cycle and facilitating proliferation of keratinocytes." (PMID 39234815, 2024). "Immunofluorescence staining showed that FGF12 expression was markedly higher in epidermal keratinocytes of lesional skin from psoriasis patients than in normal skin from healthy donors, indicating that there is a potential correlation between FGF12 and the development of psoriasis." (PMID 39234815, 2024). "Similarly, western blot results revealed that the psoriasis model phenotype in vitro, including Akt and p65 pathways, were also activated after 12 h M5 treatment, along with FGF12 and cell proliferation factor Cyclin D1." (PMID 39234815, 2024). "The role of FGF12 in the pathogenesis of psoriasis remains poorly understood." (PMID 39234815, 2024). "Moreover, we found that knockout of FGF12 specifically in mice keratinocytes induced apoptosis and inhibited aberrant proliferation of keratinocytes, which ultimately reduced the severity of psoriasis." (PMID 39234815, 2024). "In addition, immunofluorescence staining showed that the level of FGF12 was elevated in the epidermis of IMQ‐induced psoriasis mice and was strongly correlated with the pathological progression of psoriasis." (PMID 39234815, 2024). "In this study, high expression of FGF12 is observed in the epidermis of skin lesion in psoriasis patients and imiquimod (IMQ)‐induced psoriasis like‐dermatitis." (PMID 39234815, 2024). "The role of FGF12 in cell proliferation is well‐established, but its regulation and function in the context of psoriasis have not been thoroughly explored." (PMID 39234815, 2024).
pulmonary arterial hypertension (1 paper, 2022). Pulmonary arterial hypertension (PAH) is a group of diseases characterized by mean pulmonary artery pressure >20 mmHg and elevated pulmonary arterial resistance leading to right heart failure. "Intriguingly, a recent study demonstrated FGF12 as an inhibitor of vascular smooth muscle (VSM) cell remodeling in pulmonary arterial hypertension." (PMID 36012732, 2022).
renal fibrosis (1 paper, 2024). A final common manifestation of a wide variety of chronic kidney diseases characterized by glomerulosclerosis and tubulointerstitial fibrosis. "Additionally, FGF12, a member of the FGF family linked to renal fibrosis and various cellular processes, was identified." (PMID 38767678, 2024).
sarcoma (1 paper, 2024). A usually aggressive malignant neoplasm of the soft tissue or bone. "While FGF12 may reflect the aggressiveness of the tumor microenvironment, KLHL29’s varying expression levels among different sarcoma types highlight its potential as a biomarker for distinguishing tumor subtypes." (PMID 39676856, 2024).
skin inflammation (1 paper, 2024). "Therefore, we investigated the impact of FGF12 on IMQ‐induced skin inflammation by conducting immunofluorescence analysis to assess the expression levels of markers of skin inflammation and hyperproliferation, including K6." (PMID 39234815, 2024).
Tremor (1 paper, 2023). An unintentional, oscillating to-and-fro muscle movement about a joint axis. "Patient 2 manifested tremors, suggesting that the phenotypic spectrum of biallelic FGF12-related disorder may be potentially related to tremors." (PMID 37286232, 2023).
uterine sarcoma (1 paper, 2024). "It is worth noting that the overexpression of FGF12 was also observed in an independent cohort of uterine sarcoma patients and was significantly associated with a decrease in patient survival, further confirming its prognostic significance." (PMID 39676856, 2024). "The identification of Str1 as a poor prognostic factor and the discovery of FGF12 as a prognostic biomarker opens new avenues for understanding and treating this rare form of uterine sarcoma." (PMID 39676856, 2024). "In addition, an independent cohort of patients further validated the association between high FGF12 gene expression and shortened overall survival (OS) in uterine sarcoma patients, suggesting that FGF12 could potentially be a prognostic biomarker for ESS." (PMID 39676856, 2024).
West syndrome (1 paper, 2020). "Recently, a complex chromosomal rearrangement, including a much larger duplication encompassing the whole FGF12 gene and an inv dup del(9p), was reported in a patient with West syndrome." (PMID 32524056, 2020).
cancer (17 papers, 2012 to 2026). A tumor composed of atypical neoplastic, often pleomorphic cells that invade other tissues. "DACT1, VRK2, MELTF, and FGF12 have been implicated in cancers other than CC, and PRICKLE2 has been reported to correlate with CC." (PMID 32408396, 2020). "However, FGF12 has been linked to cancer progression, cardiac diseases, and nervous system disorders." (PMID 41131959, 2026). "Functional assays revealed that FGF12 expression conferred survival of cancer cells to chemotherapeutic agents, including etoposide and camptothecin." (PMID 41294881, 2025). "Mutations in FGF12, a member of the fibroblast growth factor (FGF) family, are rare (<1%) in cancer." (PMID 31850198, 2019). "However, recent studies suggest that FGF12 possesses various cellular functions beyond ion channel regulation, particularly in cancer progression." (PMID 41744813, 2026). "Similarly to FGF12, FGF14 activity has been well characterized in excitable neuronal cells, and overexpression in cancer—specifically lung and pancreatic—has been associated with worse prognosis for patients." (PMID 41131959, 2026). "Next, we examined the effect of FGF12 on cancer cell growth." (PMID 41294881, 2025). "FGF receptor inhibitors, such as FGFR tyrosine kinase inhibitors, have shown efficacy in various cancers with aberrant FGF signaling and may represent a potential treatment avenue for ESS patients with high FGF12 expression." (PMID 39676856, 2024). "CSF2RA and FGF12 are part of the Kyoto Encyclopedia of Genes and Genomes (KEGG) cancer pathway." (PMID 34282050, 2021). "These endothelial cells promoted cancer cell proliferation by secreting platelet-derived growth factor subunit B (PDGFB), which was stimulated by cancer cell-secreted vascular endothelial growth factor (VEGF), fibroblast growth factor 12 (FGF12), pleiotrophin (PTN) and neurofibromin 1 (NF1)." (PMID 24977105, 2012).
tumor (12 papers, 2016 to 2026). "Accumulating evidence indicates that the upregulation of FGF12 is associated with tumor survival, therapeutic resistance, and poor prognosis through signaling pathways independent of its canonical ion channel interactions." (PMID 41744813, 2026). "The association between the tumor cell subpopulation Str1 and its marker FGF12 with poor prognosis in ESS suggests that targeting the FGF signaling pathway could be a promising therapeutic approach." (PMID 39676856, 2024). "Given that YB1 is an RNA-binding protein with established roles in regulating tumor progression, therapy resistance, and lineage plasticity, we studied the protein–protein interaction between FGF12 and YB1." (PMID 41294881, 2025). "These molecular function analyses supported the linkage of FGF12 with tumor progression." (PMID 41294881, 2025). "The relative stability of Str1 and FGF12 may reflect their importance within the tumor microenvironment, particularly in promoting tumor cell survival and proliferation." (PMID 39676856, 2024). "Moreover, both BPV-E4- and BPV-E1^E4-mediated nucleofection of equine ACFCs brought about the upregulation of FGFR3 and FGF12 (fibroblast growth factor receptor 3 and fibroblast growth factor 12), which are known as factors promoting tumor growth and metastasis." (PMID 35216085, 2022). "Fibroblast growth factor 12 (FGF12) is a member of the fibroblast growth factor (FGF) family, whose members are broadly involved in embryonic development, tissue repair, and tumor growth." (PMID 41294881, 2025). "In this study, we reported an upregulation of FGF12 in several CRPC tumor biopsies and t-NEPC tumor cells." (PMID 41294881, 2025). "Through its interaction with YB1, FGF12 enhances the expression and stability of oncogenic lncRNAs, including NEAT1 and MALAT1, thereby strengthening adaptive transcriptional programs that support tumor persistence." (PMID 41294881, 2025). "Furthermore, overexpression of FGF12, FGF14, FGF17, FGFR1, FGFBP3 and IGFBPL1 genes was found in early tumor stage, while, overexpression of IGF1R, IGF2BP2 and INSRR was found in advanced tumor stages." (PMID 34061869, 2021). "In GSE126078, which included PDXs derived from the same parental tumor (LuCaP 173), the small-cell neuroendocrine PCa (SCNPC) line (LuCaP 173.1) exhibited higher FGF12 expression than the double-negative PCa (DNPC) line (LuCaP 173.2), supporting its upregulation in t-NEPC in vivo." (PMID 41294881, 2025).
infection (2 papers, 2022 to 2023). The state of being infected such as from the introduction of a foreign agent such as serum, vaccine, antigenic substance or organism. "Our result also showed a recovery in FGF12 expression in infection state 8, consistent with the reports." (PMID 37497545, 2023). "As the Ad-FGF12 consisted of a V5-tag sequence, infection of Ad-FGF12 was confirmed by the detection of an anti-V5 antibody." (PMID 36012732, 2022). "Meanwhile, the result of the wound-scratch migration assay indicated that the overexpression of FGF12 in ORS cells promoted the cell migration at 300 and 300 multiplicities of infection (MOI) compared to the control group which was infected with LacZ adenovirus." (PMID 36012732, 2022).
FGF12 also shares sentences with these, for which no sentence is quoted: breast carcinoma (3 papers); cleft lip (2); cleft palate (2); colorectal cancer (2); infantile epileptic encephalopathy (2); Angelman syndrome (1); aortic valve stenosis (1); Brachycephaly (1); cardiac conduction disorders (1); cerebellar ataxia (1); cervical cancer (1); dermatitis (1); developmental delay (1); Dravet syndrome (1); encephalitis (1); endometrial stromal sarcoma (1); gastric tumor (1); glioma (1); hair loss (1); heart failure (1); hereditary spastic paraplegia (1); Hypotonia (1); Idiopathic Ventricular Tachycardia (1); Limb ataxia (1); lung adenocarcinoma (1); lung carcinoma (1); Macrocephaly (1); Marfan syndrome (1); microcephaly (1); myocardial infarction (1).
A further 5 diseases each share a sentence with FGF12 in 1 paper.